YY1 (YY1 transcription factor)
Diseases named in the same sentence as YY1 in open-access papers (continued):
Sharing a sentence is not in itself a finding about the gene and the disease.
tumor (continued). "Furthermore, according to the results, the expression of YY1 in tumor tissues was up-regulated significantly than that in non-tumor tissues." (PMID 32249890, 2020). "As CARM1 has not been reported to possess corepressor activity, tumor suppressive YY1 might also utilize coactivator properties of CARM1 to activate tumor suppressor genes to inhibit tumor growth in certain cancer types." (PMID 31217904, 2019). "As PTEN is an endogenous inhibitor of the PI3K/Akt signaling and it is transcriptionally repressed by Snail, we suggest that RKIP-mediated NF-κB/YY1/Snail inhibition may trigger Akt inactivation by PTEN induction, leading to subsequent reversal of the resistant tumor phenotype." (PMID 30149591, 2018). "Here, we reported that knockdown of YY1 by lentivirus-mediated short hairpin RNA or tetracycline-inducible short hairpin RNA enhanced cisplatin-induced apoptosis and inhibition of cell proliferation, migration and invasion in the HNSCC cell lines, and inhibition of the xenograft tumor growth." (PMID 29970878, 2018). "We observed that the expression levels of the phosphorylated active form of MTOR (pMTOR) and YY1 were significantly elevated at as early as one month of age and persistently activated throughout the study period, while MYC and SLC2A1 expression was found upregulated only upon tumor formation." (PMID 25909713, 2015). "Although other undiscovered mechanisms maybe involved in the YY1-mediated tumor suppression role, the present study suggested that YY1 high-level overexpression (≥1.159) plays a negative role; i.e., acts as a tumor suppressor in PDAC." (PMID 24884523, 2014). "Furthermore, both Sp1 and YY1 expression levels correlate with KIF14 mRNA expression in primary serous OvCa tumors, demonstrating their potential role in maintaining high KIF14 levels in OvCa tumor cells." (PMID 24626475, 2014). "Moreover, while the RelA (p65) subunit of NF-κB family was shown to directly regulate YY1 expression, it was not clear if these two molecules exhibit cross talk in the regulation of gene expression and tumor survival." (PMID 23874387, 2013). "Nevertheless, it is not yet clear whether repression of Bim by YY1-RelA complex is conserved within the MM tumor progenitor cells." (PMID 23874387, 2013). "The tumor suppressor role of miR-29b2/miR-29c was clearly evidenced by gain-of-function experiments demonstrating that forced over-expression of this miRNA cluster in RMS cells is sufficient to impair the tumorigenic properties both in vitro and in vivo by repressing YY1 expression." (PMID 23443118, 2012). "YY1 was localized in the nucleus irrespective of histologic subtype, patient age, or tumor site." (PMID 22047406, 2011). "AP-2α also correlated with luminal-type tumours but not with YY1 expression or good prognosis." (PMID 20025767, 2009). "In vivo experiments have also confirmed that the absence of MRPL42 significantly suppresses tumor growth.Bioinformatics analysis suggests that the transcription factor YY1 may promote the transcription of the MRPL42 gene by binding to its upstream promoter region." (PMID 40371222, 2025). "Furthermore, PTEN acts to suppress the PI3 K/AKT pathway, however, NO inhibits NF-κB, Snail, and YY1, resulting in PTEN downregulation and subsequent suppression of PTEN-mediated PI3 K/AKT signaling, thereby influencing proliferation and apoptosis resistance pathways in tumor cells." (PMID 41036604, 2025).
tumor (continued). "Additionally, it was found that YY1 is negatively regulated by corticotropin-releasing hormone receptor-2 (CRHR2)/Urocortin-2 (Ucn2) signaling, which can result in transcriptional de-repression of Fas and can resensitize the tumor to anti-Fas antibody-mediated apoptosis." (PMID 38539569, 2024). "Therefore, we hypothesized that targeting YY1 in CD8 T cells should inhibit the expression of these receptors and, thus, prevent the inactivation of the anti-tumor CD8 T cells by these receptors, by corresponding ligands to tumor cells." (PMID 39796650, 2024). "Furthermore, YY1 can also regulate the interaction between CSCs and their microenvironment by activating the expression of cytokines and chemokines that recruit immune cells and promote the formation of a pro-inflammatory microenvironment that supports CSC survival and tumor growth." (PMID 37444616, 2023). "Therefore, SP1 (or YY1) may directly interact with the promoter region of lncRNA AFAP1-AS1 as upstream transcription factors, thereby regulating the expression of lncRNA AFAP1-AS1 and promoting or inhibiting tumor progression." (PMID 37686205, 2023). "However, clinical data on YY1-targeted therapies are currently lacking and further research, including clinical trials, is needed to fully demonstrate the safety and efficacy of YY1-targeted therapies in tumor patients." (PMID 37444616, 2023). "In addition to tumor cells, the interactions between different cells in the TME shape the unique metabolic characteristics of the microenvironment and maintain tumor growth, such as CAF, immune cells, and stromal cells, but the metabolism of YY1 in these components has rarely been reported." (PMID 37081988, 2023). "Similarly, a ubiquitous immunoreactivity of YY1 in tumor samples may account for the absence of correlation with clinical parameters or ZNF322A expression pattern." (PMID 32929330, 2020). "Interestingly, a different study showed that RKIP induction resulted in the inhibition of YY1 and sensitization to TRAIL-mediated apoptosis alongside with upregulation of DR5, while treatment of tumour cells with RKIP small interfering RNA (siRNA) reversed tumour cell sensitization to TRAIL." (PMID 31766768, 2019). "Furthermore, overexpression of YY1 was detected in several B-NHL cell lines and in silico mRNA data analyses revealed that the altered expression of YY1 might promote B cell transformation and contribute to tumor progression." (PMID 29564133, 2018). "However, while recent studies have provided further evidence of the tumor suppressive role of YY2 as opposed to the protooncogenic role of YY1, no studies have suggested that they could regulate common binding site in the same target gene antagonistically and exert opposite functions." (PMID 35246964, 2022). "When the core is absent, YY1 recruits histone deacetylase 1(HDAC1) to repress the B23 gene, a gene which suppresses multiple tumor suppressors and, hence, exhibits oncogenic effects." (PMID 25053986, 2014). "We then explored the methylation levels (beta values) of YY1 and PEBP1 across different TCGA tumors and found that PEBP1 is highly methylated in LGG, LAML, LUAD, LUSC, and HNSC, among other tumors, while YY1 is not significantly methylated in any tumor." (PMID 37894300, 2023). "Interestingly, the Yy1 gene regulatory network seemed to be mostly FUT9-specific, but not tumor-specific." (PMID 32927726, 2020). "In the present study, our results reveal that the YY1/PGC-1β axis regulates HCC cell lipid metabolic reprogramming under both normoxic and hypoxic conditions, suggesting that this pathway is common in tumor cells, regardless of their location in tumor tissue." (PMID 31695789, 2019). "To determine whether KIF14 overexpression in OvCa tumors could also be linked to transcriptional regulation, we measured mRNA expression of Sp1, YY1 and HSF1 in a subset of OvCa tumor tissues with (15 samples) and without (50 samples) KIF14 genomic gain." (PMID 24626475, 2014).
tumor (continued). "Additionally, all the mixed datasets containing samples obtained from different NSCLC subtypes, showed to have a significantly high YY1 and significantly low RKIP expressions compared to N, but without any difference in the expression within the various tumor subtypes." (PMID 35205667, 2022). "Unlike YY1, YY2 expression is downregulated in tumor tissues, and might act as a tumor suppressor." (PMID 32226547, 2020). "Interestingly, our results showed that YY1 inhibition of PGC-1β expression occurs independent of hypoxia-inducible factor-1α (HIF-1α), a key regulator of hypoxic response that has been known to promote tumor cell lipid accumulation." (PMID 31695789, 2019).
cancer (299 papers, 2008 to 2025). A tumor composed of atypical neoplastic, often pleomorphic cells that invade other tissues. "YY1 is overexpressed in many cancers, and its high expression is associated with poor clinical outcomes and resistance to chemotherapy and immunotherapy." (PMID 40904706, 2025). "Bioinformatic analysis of public datasets supported these findings in BC, showing YY1 overexpression in multiple cancer types and its association with poor outcomes in BC." (PMID 41009346, 2025). "YY1 is a host transcription factor that can act as both activator and repressor, and its overexpression is linked to various cancers." (PMID 40953061, 2025). "Beyond its role in T cells, YY1 also influences cancer-associated fibroblasts by enhancing their recruitment and activation through modulation of TGF-β and PDGF signaling pathways." (PMID 41327312, 2025). "This upregulation is likely to be responsible for the YY1 interaction with RelB and p50, and is associated to an inflammatory microenvironment that enhances the cancer progression." (PMID 39904836, 2025). "YY1 has additionally been implicated in neurodevelopmental disorders, neurodegeneration 72, cardiac development 73, and cancer." (PMID 40502787, 2025). "Expression of YY1 has been associated with emergence of drug resistance, cancer metastasis and poor prognostic outcomes." (PMID 38351178, 2024). "YY1 regulates the protein stability and expression of many different cancer-associated genes as well." (PMID 39796650, 2024). "HnRNP L’s pro-cancer effects have been determined to be primarily caused by the stimulation of the YY1/PD-L1 axis." (PMID 38539569, 2024). "Though YY1 has been determined to be linked to cancer progression and treatment resistance, the exact downstream effects of YY1 overexpression in cancer are still being explored." (PMID 38539569, 2024). "In prostate cancer, the development of malignant tumors is closely associated with the simultaneous enrichment of YY1 and H3K27ac ChIP-seq signals in the specific enhancer of the IL-6 gene in M2 macrophages." (PMID 38586584, 2024). "This process, which ends in the upregulation of PD-1 and LAG-3, is clearly regulated by YY1, and causes T cell exhaustion and the persistence of various cancers." (PMID 39796650, 2024). "YY1 is known to be implicated in the pathogenesis of various cancer cells as an immunosuppressive factor." (PMID 38539569, 2024). "Previous studies have demonstrated the close association between YY1 expression and the prognosis of various cancers." (PMID 38347631, 2024). "YY1 regulates the protein stability and gene expression of many different cancer-associated genes, as well as the expression of LAG-3 directly at the promoter region." (PMID 39796650, 2024). "A synergistic antitumor effect is exerted when both KDM5C and YY1 are depleted, and targeting YY1 appears to be a vulnerability in KDM5C-deficient cancer cells." (PMID 39433896, 2024). "Per the findings, YY1 was identified as a crucial transcriptional activator of cancer autophagy-related genes and promoted the proliferation and aggressiveness of cancer cells associated with enhanced ATG4B-mediated autophagy." (PMID 37724907, 2023). "YY1′s dual role as a transcription factor can be explained by the cellular contexts or mutated binding sites within the BIRC5 promoter of cancer cells, impacting the binding of YY1." (PMID 37686541, 2023). "In some cases of cancer, YY1 has been reported to consistently exhibit a point mutation at T372R of YY1′s DNA-binding zinc finger." (PMID 37686541, 2023). "Previous studies have shown that increased YY1 expression is associated with worse clinical features in many cancers." (PMID 37724907, 2023). "Particularly, the NF-κB/Snail/YY1/RKIP loop, which is dysregulated in cancer, reveals that, while the overexpression of NF-κB and Snail causes YY1 activation, the eventual induction of RKIP expression downregulates its precursors: NF-κB, Snail and YY1." (PMID 37686541, 2023).
cancer (continued). "YY1 appears to be a potential drug target and a diagnostic or prognostic marker for the detection of cancers." (PMID 35408813, 2022). "YY1 is a transcription factor that has been shown to play an important role in the development of cancer, and there is mounting evidence that YY1 is significantly linked to the growth of CRC cells and can be used to predict prognosis in CRC patients." (PMID 36497293, 2022). "have found that the loss of YY1 leads to, among others, a reduction in basal oxygen consumption rates, maximal respiratory capacity, and ATP turnover, essential for cancer proliferation." (PMID 35719931, 2022). "YY1 is involved with both stimulation and suppression of tumour growth, being overexpressed in several cancer types and associated with a poor outcome." (PMID 36615513, 2022). "Emerging evidence indicates that the development of lethal YY1-mediated cancer phenotypes is associated with the presence of or enrichment in cancer stem-like cells." (PMID 33728560, 2021). "Given their observed anti-cancer role, we propose YY1 and BCL2L15 as candidate diagnostic and prognostic CRC biomarkers." (PMID 34445183, 2021). "YY1 is involved in differentiation and proliferation, is overexpressed in cancer, and its genetic manipulation has been associated with phenotypic reversion between MCF10A and MCF7." (PMID 34572749, 2021). "Clearly, defining the molecular mechanism underlying the contrasting behavior of YY1 in cancer remains an interesting task." (PMID 32226547, 2020). "In this review, we will outline the involvement of YY1 in tumorigenesis, focusing on its role in regulating multiple hallmarks of cancer and the molecular mechanism(s) underlying them." (PMID 32226547, 2020). "YY1 is highly expressed in many cancers, whereby it is associated with cell proliferation, survival, and metabolic reprogramming." (PMID 32226547, 2020). "We conclude that the cancer-associated transcription factors YY1 and MAX exhibit expressional heterogeneity in FTCs." (PMID 33063251, 2020). "The enzyme was highly expressed in cancerous tissues, where it stabilized a known gene with the potential to cause cancer called YY1." (PMID 31956270, 2020). "YY1 has been associated with a regulatory loop with cancer stem cell transcription factors (SOX2, OCT4, BMI1) during the cross-talk between the NF-kB/PI3K/AKT pathways." (PMID 31867044, 2019). "The relationship between C/EBPs and inflammation has been reported 32 and YY1 is also a transcription factor associated with inflammation and cancer." (PMID 30761253, 2019). "Owing to its role in processes that upon deregulation are linked to malignant transformation, YY1 has been implicated as a major driver of many cancers." (PMID 31824839, 2019). "YY1 is tightly associated with cancer; however, a relationship between Amtn and tumors has been reported in a few studies." (PMID 30761253, 2019). "While YY1 has been shown to play opposing roles in cancer, owing to its ubiquitous expression YY1 has also been implicated in embryonic development and cellular lineage differentiation." (PMID 31824839, 2019). "YY1 is deregulated and implicated in several cancers including solid tumors and hematological malignancies like B-NHL." (PMID 29564133, 2018). "An underlying mechanism of DR induction by RKIP in cancer cells is through inhibition of the NF-κB/YY1 cascade." (PMID 30149591, 2018). "The abnormal expression of YY1 has been reported in various types of cancers, and its abnormal expression has been linked to poor prognosis in cancer patients." (PMID 29470526, 2018).